CSPG5 (chondroitin sulfate proteoglycan 5)
Description:
May function as a growth and differentiation factor involved in neuritogenesis. May induce ERBB3 activation.
Synonyms: NGC
Tractability: Antibody: UniProt places it where antibodies can reach, with high confidence; its Gene Ontology location is reachable by antibodies, with high confidence; UniProt predicts a signal peptide or a membrane-spanning region; the Human Protein Atlas places it where antibodies can reach. PROTAC: ubiquitination databases record sites on it; its protein half-life has been measured.
Gene: Protein-coding gene on chromosome 3 (47,562,238 to 47,580,792, reverse strand). Ensembl gene ENSG00000114646.
Subcellular location: Cell membrane; Synaptic cell membrane; Endoplasmic reticulum membrane; Golgi apparatus membrane; Cell surface; Secreted
Subcellular location (Human Protein Atlas): Cytosol; Golgi apparatus; Plasma membrane; Vesicles; Predicted to be secreted
Pathways (Reactome):
Disease: Defective B3GALT6 causes EDSP2 and SEMDJL1; Defective B3GAT3 causes JDSSDHD; Defective B4GALT7 causes EDS, progeroid type; Defective CHST14 causes EDS, musculocontractural type; Defective CHST3 causes SEDCJD; Defective CHSY1 causes TPBS
Metabolism: CS-GAG biosynthesis; CS/DS degradation; DS-GAG biosynthesis; Glycosaminoglycan-protein linkage region biosynthesis
Gene Ontology:
Molecular function: protein binding; growth factor activity
Biological process: axon regeneration; cytoskeleton organization; glial cell projection elongation; intracellular transport; nervous system development; positive regulation of substrate adhesion-dependent cell spreading; regulation of synaptic vesicle exocytosis; signal transduction
Cellular component: extracellular region; Golgi apparatus; Golgi-associated vesicle membrane; cell surface; endoplasmic reticulum membrane; Golgi lumen; Golgi membrane; lysosomal lumen; membrane; plasma membrane; postsynaptic membrane; synaptic membrane; GABA-ergic synapse; glutamatergic synapse
Genetic constraint (gnomAD): Loss-of-function variants: 24 observed, 37.65 expected, observed/expected ratio (o/e) 0.64, 90% interval 0.46 to 0.9. The upper end of that interval is the gene's LOEUF score, 0.9, which puts it in group 3 of 6, group 1 being the genes least tolerant of losing a copy. Missense variants: 579 observed, 648.97 expected, observed/expected ratio (o/e) 0.89, 90% interval 0.83 to 0.96. Synonymous variants: 268 observed, 273.61 expected, observed/expected ratio (o/e) 0.98, 90% interval 0.89 to 1.08.
Homologues: Orthologues: chimpanzee CSPG5 (99% identical), macaque CSPG5 (97% identical), dog CSPG5 (89% identical), pig CSPG5 (88% identical), rat Cspg5 (87% identical), mouse Cspg5 (87% identical), guinea pig CSPG5 (79% identical), tropical clawed frog cspg5 (47% identical), zebrafish cspg5a (31% identical), zebrafish cspg5b (27% identical).
Diseases named in the same sentence as CSPG5 in open-access papers:
CSPG5 is named in the same sentence as 20 diseases in open-access papers, as found by Europe PMC text mining. Sharing a sentence is not in itself a finding about the gene and the disease. The quoted sentences say what the papers report.
breast carcinoma (3 papers, 2020 to 2022). "Chondroitin sulfate proteoglycan 5 (CSPG5) encodes human chondroitin GSPG5, which is related to immune-related genes that are prognostic indicators of breast cancer and liver cancer patients." (PMID 35087563, 2021). "Only one study stated the CSPG5 as a prognostic factor for breast cancer based on immunohistochemical analysis." (PMID 32579175, 2020). "For chondroitin sulfate proteoglycan 5 (CSPG5), one study mentions it could be served as a prognostic factor for breast cancer based on immunohistochemical analysis." (PMID 35932027, 2022).
hepatocellular carcinoma (2 papers, 2023). A malignant tumor that arises from hepatocytes. "Similarly, a study that investigated CSPG5 and the prognosis of hepatocellular carcinoma indicated that CSPG5 is related to the transcription factors EZH2 and B-Myb, which reportedly play critical roles in EMT and cell cycle progression." (PMID 37443739, 2023).
cataract (1 paper, 2023). Partial or complete opacity of the crystalline lens of one or both eyes that decreases visual acuity and eventually results in blindness. "In this study, we aimed to identify the presence of CSPG5 in human lens samples, as well as the relationship between CSPG5 expression and cataract development." (PMID 37443739, 2023).
cognitive deficits (1 paper, 2025). "Conversely, the downregulation of genes like NPY, CSPG5, VGF, ADAMTS2 and GPC2 among others, in astrocytes and other cell-types points to impaired neuroprotective mechanisms and compromised synaptic function contributing to cognitive deficits." (PMID 41282152, 2025).
glioma (1 paper, 2025). A benign or malignant brain and spinal cord tumor that arises from glial cells (astrocytes, oligodendrocytes, ependymal cells). "This analysis identified CSPG4, PTPRZ1, and BCAN as the most highly expressed and concordant ECM targets in adult gliomas, while GPC1, CSPG5, and TNR were the top concordant targets in pediatric gliomas." (PMID 40517137, 2025).
injury (1 paper, 2025). Damage inflicted on the body as the direct or indirect result of an external force, with or without disruption of structural continuity. "ECM-related proteins such as SPOCK1 and CSPG5 were also integrated within the network, consistent with their potential involvement in matrix remodeling during acute brain injury." (PMID 41152969, 2025).
retinal disease (1 paper, 2017). "According the paper, among these DEGs, PTPRG, CSPG5 and NAV3 are at loci associated with retinal disease; MFAP3L, CSPG5 and PAK1IP1 locate in the regions carrying SNP's significantly associated with AMD." (PMID 28924976, 2017).
tumor (7 papers, 2010 to 2025). "Six sex-specific, Esr1-dependent transcripts–A1bg, Fmo3, Cabyr, Cspg5, Mthfd1l, Tff3–are strongly implicated in hepatocarcinogenesis based on their expression, prognostic power, or oncogenic/tumor suppressive properties." (PMID 34068249, 2021). "The tumor tissues displayed an enriched expression of transcription factors (e.g., Dlx2, Gbx2, Foxb1, and Nkx2.2) critical for brain development, tanycyte markers (e.g., Ptprz1, Fabp7, Crym, and Gja1), and differentiation markers (e.g., Dcx, Olig1, and Cspg5)." (PMID 33863883, 2021). "CSPG5 is only expressed in the human brain, and a study showed that it has a new function that binds to ERBB3 tyrosine kinase, and the ERBB3 somatic mutation is a potential tumour driver." (PMID 33962640, 2021). "Using three spatially-enriched marker genes for each tumor subregion (CT: BCAN, CSPG5, TOP2A; Pseudo: HILPDA, IGFBP5, LGALS3; and MVP: MGP, LUM, THBS1) we identified distinct sub-populations of malignant cells from the scRNA-seq data." (PMID 41366031, 2025). "The concordant changes in protein expression results with the values detected at the gene expression can be observed in all the evaluated parameters of integrin αV, brevican, CSPG-5, versican, integrin β-5, and CD44 and only in tumor staining in the case of MDM2, MMP2, and FLT-4." (PMID 39595920, 2024).
cancer (3 papers, 2010 to 2025). A tumor composed of atypical neoplastic, often pleomorphic cells that invade other tissues. "Among them, Cspg5, Fbn1, Thbs1, Pdpn, Etv4, Unc5a, Ntn1, and Nat8l were associated with the OC prognosis; Cspg5, Fbn1, Pdpn, and Unc5a were correlated with patient age; Fbn1, Mycn, Nat8l, Unc5a, and Ntn1 were significantly correlated with individual cancer stage." (PMID 36829196, 2023).
CSPG5 also shares sentences with these, for which no sentence is quoted: schizophrenia (4 papers); liver cancer (2); ovarian carcinoma (2); retinal degeneration (2); COVID-19 (1); learning disability (1); Leber congenital amaurosis (1); Lissencephaly (1); melanoma (1); neurodegenerative disease (1); prostate carcinoma (1).